ODC1 (ornithine decarboxylase 1)
Diseases named in the same sentence as ODC1 in open-access papers (continued):
Sharing a sentence is not in itself a finding about the gene and the disease.
cancer (continued). "Although ODC1 activity is required for normal growth, it is elevated in many types of human cancers such as CRC and liver cancer." (PMID 36457036, 2022). "Further, high ODC1 expression is correlated with poor clinical outcome in cancers, suggesting that it can serve as a drug target for cancer therapy." (PMID 35906392, 2022). "c-Myc on the other hand positively regulates ODC1 gene expression and along with spermine synthase promotes cancer cell survival." (PMID 34067619, 2021). "While DFMO shows anti-DIPG activity, one method by which cancer cells can compensate for the effect of ODC1 inhibition on polyamine synthesis is by increasing uptake of polyamines via polyamine transporters." (PMID 33579942, 2021). "Only lower ODC1 expression ratio in M1 than M0 cancers resulted from significantly lower gene expression in tumors from M1 patients (by 3.5-fold)." (PMID 32872669, 2020). "Fold change in ODC1 was significantly lower (by 4.1-fold) in cancers metastasizing to distant organs as well." (PMID 32872669, 2020). "After 72 h of ODC1 RNAi treatment we detected more activated caspase 3/7 activity in the treated cancer cells than in the untreated HT1376 cells." (PMID 32123240, 2020). "When ODC1 expression patterns were inspected more thoroughly, we found that ODC1 expression in patients with more advanced cancers decreased in tumors but increased in adjacent tissue." (PMID 32872669, 2020). "Gene expression profile analysis from the NanoString Cancer Metabolism panel showed a significant decrease in ODC1 and an increase in TSC2 mRNA expression in LCC9 xenografts when these were co-treated with CB-839 and everolimus." (PMID 31428575, 2019). "ODC1 itself was amplified in only 3% of cancers and had copy number gain in 13% often in the same cancers with MYC amplifications." (PMID 29240775, 2017). "We further noted the increased expression of ODC1 in late stage and in higher grade cancers in these laser captured Affymetrix samples." (PMID 29240775, 2017). "ODC1 was expressed in all subtypes but we noted the significantly increased expression in the copy number high cancers." (PMID 29240775, 2017). "Notably, genes including CAV1, ITGB1, BNIP3, and YTHDF2 were associated with the AKT signalling pathway, suggesting a functional link between ODC1 activity and cancer progression." (PMID 41803527, 2026). "Targeting oncogenic c-MYC and ODC1 has emerged as a strategy for cancer treatment." (PMID 36457036, 2022). "Potential effect of IL-4 and IL-13 (250 ng/mL, 24 h) on the expression of genes encoding proteins relevant for cancer development by facilitating angiogenesis (HIF1A and VEGFA), inflammation (PTGS2, NOS2, CCL2), and metabolic reprogramming (GLUT1, ODC1, NOS2) was evaluated." (PMID 32512917, 2020). "The elevated levels of ODC1 mRNA noted in those cancers with poor prognostic factors prompted us to directly examine whether ODC1 mRNA levels themselves were prognostic for recurrence or survival." (PMID 29240775, 2017). "Thus, administrating ODC1 inhibitor such as DFMO in cancer can be a good treatment regimen." (PMID 35906392, 2022). "Intracranial implantation of ODC1-knockdown GBM cells resulted in significantly extended survival compared with a non-target control, indicating that SPD production by cancer cells is partially responsible for GBM growth." (PMID 39561012, 2024). "In contrast, ODC1 inhibition using difluoromethylornithine (DFMO) primarily affected putrescine synthesis, but had off-target effects on both cancer and non-cancer cells." (PMID 37884518, 2023). "Polyamine blocking therapy (PBT), particularly, blocking ODC1 or SMOX activity, has shown promising therapeutic potentials in several types of cancer." (PMID 37653021, 2023). "Further, Ornithine decarboxylase 1 (ODC1) is a critical enzyme using ornithine from urea cycle for polyamine biosynthesis, and is frequently deregulated in cancer." (PMID 35906392, 2022).
cancer (continued). "ODC1, SAT1, SMOX, and SRM genes are known to decrease cell proliferation in several cancer cell lines." (PMID 31417867, 2019). "In our initial analysis we noted increased expression of ODC1, spermidine synthase (SRM) spermine synthase (SMS) and decreased expression of SAT1 in cancers (n = 176) as compared to normal endometrial samples (n = 12)." (PMID 29240775, 2017). "What’s more, ferroptosis-iron overload-WNT/MYC-ornithine decarboxylase 1(ODC1)-polyamine-H2O2 axis is a positive feedback loop that amplifies ferroptosis and polyamine sensitizes cancer cells to ferroptosis in the way of extracellular vesicles and polyamine supplementation." (PMID 41502519, 2025). "Moreover, ODC1 expression and activity were also mediated by p5344,45 and PTEN–PI3K–mTOR complex 1 (mTORC1) pathway in various cancer cells." (PMID 39251577, 2024). "Similarly, Ornithine decarboxylase (ODC1) is involved in polyamine biosynthesis and is upregulated in tumors, especially in MYC-driven cancers." (PMID 37760568, 2023). "The results revealed that polyamines are associated with cancer survival and DFMO-induced cell death but not with ODC-1 activity." (PMID 34638596, 2021). "In addition, the local expression of key pathway enzymes (ARG1, ARG2, DDAH1, DDAH2, NOS2, ODC1, PRMT1, and PRMT5), as potential therapeutic targets, was evaluated in reference to cancer pathology." (PMID 32872669, 2020). "If so, the ODC1 RNAi approach we describe here may be suitable to study the functional consequences of LINE-1 hypomethylation and its role in the carcinogenesis process of many other cancer entities as well." (PMID 32123240, 2020). "Furthermore, LINE-1 induction enabled by ODC1 interference provides a new experimental model to study mechanisms and consequences of LINE-1 activation in the etiology and progression of UC as well as presumably other cancers." (PMID 32123240, 2020).
infection (21 papers, 2009 to 2025). The state of being infected such as from the introduction of a foreign agent such as serum, vaccine, antigenic substance or organism. "Put+ supplementation also increased the levels of Odc1 compared to arg+/spd+ at 4 and 24h of infection." (PMID 37000792, 2023). "We further showed that the infection of RYSV in leafhopper vector upregulates ODC1 expression but inhibits OAZ1 expression, which would facilitate the conversion of ornithine to PUT." (PMID 37676339, 2022). "On the other hand, the Slc7a1 L-arginine transporter was downregulated during the infection, and Nos2, Arg1, Odc1, and Slc7a2 were expressed at similar levels in uninfected macrophages." (PMID 35202090, 2022). "In our study, we found that the expression of ODC1 and SRM were both upregulated in the HBV replication cells and cell models of infection." (PMID 32373551, 2020). "Mechanistic studies using an in vitro human tonsil organoid infection model revealed that HIV infection of T cells also resulted in increased polyamine synthesis, which was dependent on the activities of caspase-1, IL-1β, and ornithine decarboxylase-1." (PMID 36693889, 2023). "Overall, these results clearly demonstrated that polyamine synthesis is required for efficient KSHV lytic reactivation and de novo infection, and that FDA-approved drugs inhibiting the key enzyme ODC1 can be used to block KSHV lytic reactivation and the following viral dissemination." (PMID 35486659, 2022). "However, in this study, we find that the infection of the cytorhabdovirus rice stripe mosaic virus (RSMV) in leafhopper vector could significantly upregulates both OAZ1 and ODC1 expression, which also facilitates the conversion of ornithine to PUT expression." (PMID 37676339, 2022). "Previous studies have shown that polyamine depletion by difluormethylornithine (DFMO), a specific nontoxic inhibitor of ODC1, could inhibit the infection of mammalian cells by vertebrate rhabdoviruses, including RABV and vesicular stomatitis virus (VSV)." (PMID 37676339, 2022). "Although the levels of Cat1/Slc7a12 Cat2/Slc7a22 Arg1, and Odc1 did not behave as expected during infection, increased levels of the Arg2 transcript level were not reflected by the increased competition of cytoplasmatic arginine with NOS2 because of its mitochondrial localization." (PMID 35202090, 2022). "However, we did not observe an increase in the Odc1 transcription during infection." (PMID 35202090, 2022).
bacterial infections (1 paper, 2023). "Recently, the role of ODC1 in modulating gastric and colonic inflammation in macrophages after bacterial infections were reported." (PMID 37308808, 2023).
neurodegenerative disease (1 paper, 2024). A disorder of the central nervous system characterized by gradual and progressive loss of neural tissue and neurologic function. "ODC1 is a critical enzyme for neurodegenerative disease through converting ornithine into putrescine, which is the substrate of MAO‐B for astrocytic GABA production." (PMID 38715318, 2024).
ODC1 also shares sentences with these, for which no sentence is quoted: human African trypanosomiasis (17 papers); oral cancer (6); pancreatic cancer (5); bladder cancer (4); malaria (4); alopecia (3); diffuse intrinsic pontine glioma (3); esophageal cancer (3); esophageal squamous cell carcinoma (3); multiple myeloma (3); papilloma (3); skin cancer (3); leukaemia (2); neurodevelopmental disorder (2); ovarian carcinoma (2); psoriasis (2); abdominal aortic aneurysm (1); adenocarcinoma (1); alcohol abuse (1); amyloid (1); Angelman syndrome (1); Anxiety (1); Arrhythmia (1); astrocytoma (1); autoimmune disease (1); Barth syndrome (1); benign prostatic hyperplasia (1); bipolar disorder (1); Breast Tumor (1); Chronic colitis (1).
A further 53 diseases each share a sentence with ODC1 in 1 paper.